BMP5 (bone morphogenetic protein 5)
Diseases named in the same sentence as BMP5 in open-access papers (continued):
Sharing a sentence is not in itself a finding about the gene and the disease.
pancreatic cancer (4 papers, 2018 to 2020). "Low expression levels of BMP-5 were detected in various pancreatic cancer cells compared to normal samples." (PMID 32050622, 2020). "BMP5 inhibits the proliferation and promote migration and invasion of pancreatic cancer cell and thus exhibit a biphasic role." (PMID 31973134, 2020). "BMP-5 displayed a biphasic role as being both detrimental and beneficial: BMP-5 treatment inhibited the growth of pancreatic cancer cells but promoted migration and invasion." (PMID 32050622, 2020). "Additionally, BMP5 together with BMP4 have a dualistic role in some pancreatic cancer cell lines, acting simultaneously as anti-proliferative factors inhibiting cell growth as well as pro-metastatic factors through stimulation of cell migration and invasion." (PMID 32968094, 2020). "However, in lung, breast, liver, and pancreatic cancer, BMP5 could correlated with at least one or more Smad effectors." (PMID 30572883, 2018).
prostate carcinoma (4 papers, 2012 to 2020). A carcinoma that arises from epithelial cells of the prostate gland. "Therefore, it is possible that rs3734444 might directly or indirectly, through other linked SNPs, influence BMP5 expression, interaction between prostate cancer cells and the bone microenvironment, and ultimately progression to bone metastasis." (PMID 22844442, 2012). "Using a mouse model of prostate cancer highly enriched in cancer stem cells, we finally show that inhibition of BMP5 signaling is sufficient to delay cancer progression from basal cells in the prostate and in the skin." (PMID 32894216, 2020). "For example, BMP6, a member of the BMP5/6/7 subfamily, is upregulated in prostate cancer and contributes to cancer progression." (PMID 32894216, 2020). "Specifically, the expression of BMP-3 and BMP-5 was relatively higher whereas the expression of BMP-7 was comparatively lower in prostate cancer tissue than normal tissue." (PMID 31137764, 2019). "A positive correlation was observed between the metastatic potential of these prostate cancer cell lines and BMP5 expression." (PMID 22844442, 2012). "Our obtained results revealed that BMP5 expression was down-regulated in bladder, breast, colorectal, gastric, kidney, lung, ovarian, prostate cancer and sarcoma compared to the expression level in normal cases whereas up-regulation was only found to be in the central nervous system (CNS) cancer." (PMID 31973134, 2020). "Furthermore, amplifications of the BMP5 gene loci appeared to be more prevalent in tumors with a higher Gleason score and occurred in 50% of prostate tumors, which might account for the abnormal gene expression patterns of BMP5 in prostate cancer." (PMID 22844442, 2012). "CASP3 rs4862396, BMP5 rs3734444 and IRS2 rs7986346 were found to be the independent prognostic markers for patients receiving ADT for prostate cancer." (PMID 22844442, 2012). "It suggested that CASP3 rs4862396, BMP5 rs3734444 and IRS2 rs7986346 may be useful markers for predicting the survival in patients receiving ADT for prostate cancer." (PMID 22844442, 2012). "Our results suggest that CASP3 rs4862396, BMP5 rs3734444 and IRS2 rs7986346 may affect the survival in patients after ADT for prostate cancer, and the analysis of these SNPs can help identify patients at higher risk of poor outcome." (PMID 22844442, 2012).
rheumatoid arthritis (4 papers, 2011 to 2020). A chronic, systemic autoimmune disorder characterized by inflammation in the synovial membranes and articular surfaces. "In patients with rheumatoid arthritis, stimulation with IL-1β induced BMP-2 and BMP-6, but not BMP-4, BMP-5, or BMP-7 in fibroblast-like synoviocytes." (PMID 32290085, 2020).
breast tumors (3 papers, 2020 to 2023). "For example, BMP5 (bone morphogenetic protein 5) was downregulated in breast tumors relative to normal tissues and its downregulation was associated with cancer recurrence." (PMID 32774369, 2020).
colon carcinoma (3 papers, 2020 to 2024). "Studies of the transfection of colon carcinoma cells with a BMP5-expressing viral vector demonstrated that these cells overexpress a cell cycle regulator and tumor suppressor, cyclin-dependent kinase inhibitor 1C (CDKN1C), compared to cells in which BMP5 is down-expressed." (PMID 32722068, 2020).
lung adenocarcinoma (3 papers, 2019 to 2021). A carcinoma that arises from the lung and is characterized by the presence of malignant glandular epithelial cells. "In the testing cohort including 93 lung adenocarcinoma patients, immunohistochemistry (IHC) was performed to verify BMP5 protein expression and its association with prognosis." (PMID 34745928, 2021). "IHC results revealed that BMP5 protein was also downregulated in lung adenocarcinoma and higher expression was markedly associated with better prognosis (HR: 0.44, 95% CI: 0.23–0.85, p: 0.0145)." (PMID 34745928, 2021). "Kaplan–Meier survival curve revealed that BMP5 expression levels were significantly associated with overall survival in lung adenocarcinoma patients." (PMID 34745928, 2021). "For example, higher BMP-5 expression is linked to female patients and lung adenocarcinoma (compared to male patients and squamous cell carcinoma), although the overall expression of BMP-5 is inhibited in non-small-cell lung cancer (NSCLC) tissues compared with adjacent normal tissues." (PMID 32050622, 2020). "First, CHRDL1 as a BMP signaling antagonist suppresses tumor metastasis but co-expressed with BMP5 in lung adenocarcinoma." (PMID 34745928, 2021). "The positive coefficient indicated a positive correlation between the screened module and BMP5, and a higher coefficient with a statistically significant p-value indicated a stronger correlation with BMP5 and prognosis in lung adenocarcinoma." (PMID 34745928, 2021). "Based on significant differential expression and superior prognostic value, BMP5 has the potential to become a crucial target for the treatment of lung adenocarcinoma." (PMID 34745928, 2021). "The lower the expression of BMP5, the shorter the OS, and the poorer the prognosis in lung adenocarcinoma." (PMID 34745928, 2021). "It is necessary for CHRDL1 to explore the regulatory relationship of CHRDL1 with BMP5 and its role in lung adenocarcinoma." (PMID 34745928, 2021). "In conclusion, BMP5 is differentially expressed and can accurately evaluate prognosis as an independent protective factor in lung adenocarcinoma." (PMID 34745928, 2021). "Consistent with public database analysis, higher expression of BMP5 protein in lung adenocarcinoma indicated better prognosis." (PMID 34745928, 2021). "BMP5 was identified as an independent protective prognostic factor, and higher BMP5 expression indicated better clinical outcomes in lung adenocarcinoma." (PMID 34745928, 2021). "The results showed that BMP5 expression was low in primary lung adenocarcinoma compared with adjacent normal tissues, and was even lower in metastatic lymph nodes." (PMID 34745928, 2021). "The results from the Kaplan–Meier plotter from 719 patients with lung adenocarcinoma also supported the prognostic value of BMP5 (HR: 0.48, 95% CI: 0.38–0.61, p: 9e-10 < 0.001) and GDF10 (HR: 0.73, 95% CI: 0.57–0.92, p: 0.0085 < 0.001) from TCGA-LUAD." (PMID 34745928, 2021). "BMP5 is a potential crucial target for lung adenocarcinoma treatment based on significant differential expression and superior prognostic value." (PMID 34745928, 2021). "Consistently, we also found that GIMAP8, as a BMP5 co-expressed hub gene, was downregulated in tumor tissues, and its higher expression indicated better prognosis in lung adenocarcinoma." (PMID 34745928, 2021). "Interestingly, CHRDL1, the BMP antagonist, was found to be co-expressed with BMP5, and both were screened for their significant prognostic protective value in lung adenocarcinoma in the current study." (PMID 34745928, 2021). "However, the diagnostic value of ANOS1 and its regulatory relationship with BMP5 are currently unclear, and there is a large value in future exploration in lung adenocarcinoma." (PMID 34745928, 2021). "BMP5 is expected to become an important target for the treatment of lung adenocarcinoma." (PMID 34745928, 2021).
lung adenocarcinoma (continued). "Based on BMP5 and closely related hub genes such as CHRDL1, GIMAP8, and KAL1, we constructed and improved a prognostic risk model that effectively evaluated the prognosis of lung adenocarcinoma." (PMID 34745928, 2021). "The correlation between BMP5 and EGFR expression and mutations suggests that BMP5 may affect EGFR-targeted therapy in lung adenocarcinoma." (PMID 34745928, 2021). "To further explore the value of BMP5 in clinical treatment, we first analyzed the correlation of mRNA expression between BMP5 and EGFR/STK11, which are critical molecular in targeted therapy and immunotherapy of lung adenocarcinoma." (PMID 34745928, 2021). "We screened and verified four differentially expressed BMPs (BMP2, BMP5, BMP6, and GDF10) and one BMPR (ACVRL1), which all were downregulated in lung adenocarcinoma tissues." (PMID 34745928, 2021). "Among eight deBMPs/BMPRs, only BMP5 (HR: 0.59, 95% CI: 0.44–0.79, p: 4e-04 < 0.001) and GDF10 (HR: 0.74, 95% CI: 0.56–0.99, p: 0.0444 < 0.05) had prognostic value, and the higher expression of both indicated a better prognosis in lung adenocarcinoma." (PMID 34745928, 2021). "BMP2, BMP5, BMP6, GDF10, and ACVRL1 were verified as downregulated in lung adenocarcinoma." (PMID 34745928, 2021).
non-small cell lung carcinoma (3 papers, 2017 to 2020). A group of at least three distinct histological types of lung cancer, including non-small cell squamous cell carcinoma, adenocarcinoma, and large cell carcinoma. "While there was no report about the prognostic function of BMP5, Pro–surfactant protein B (pro-SFTPB) was reported as a promising blood biomarker for non-small-cell lung cancer." (PMID 29152081, 2017).
prostate tumor (3 papers, 2012 to 2020). "This correction of prostate tumor phenotype by Bmp5 loss was still observed 9 weeks after Cre induction." (PMID 32894216, 2020).
skin tumor (3 papers, 2014 to 2020). "Strikingly, Bmp5 gene inactivation or BMP signaling inhibition with a small molecule inhibitor are also sufficient to delay prostate and skin cancer initiation of Pten-deficient mice." (PMID 32894216, 2020). "In contrast, up-regulation of BMP5 was only reported in blood, head-neck, and skin cancer." (PMID 31973134, 2020). "Interestingly, prostate and skin tumor phenotypes could also be dampened by overexpression of GATA3 in these tissues indicating that both Gata3 and BMP5 are key players in Pten-deficient cancer progression." (PMID 32894216, 2020).
colon adenocarcinoma (2 papers, 2014 to 2023). "BMP5 (bone morphogenetic protein 5) downregulation has been implicated in the EMT processes in colon adenocarcinoma." (PMID 36674824, 2023).
diabetes (2 papers, 2020 to 2025). "Whether BMP5 contributes to a protective response to stress in the context of diabetes remains to be further investigated." (PMID 40471239, 2025). "Furthermore, BMP5 expression was significantly higher in beta cells derived from donors with type 2 diabetes than in beta cells from donors without diabetes (1.2-fold, p<0.001)." (PMID 40471239, 2025).
gastric cancer (2 papers, 2009 to 2022). A primary or metastatic malignant neoplasm involving the stomach. "Examples of such escape include the mutation of SMAD4 in pancreatic ductal adenocarcinoma (PDAC) and gastric cancer (GC), the TβR I mutation in colon cancer, and even mutations in genes that encode TGF-β ligands (BMP5), receptors (TβR II, AVCR2A, BMPR2), and SMADs (SMAD2 and SMAD4)." (PMID 35461253, 2022). "The genes PLA2G4A, BMP5, MMP6, KNNMB4 and DYM were candidates for the GP202 gastric cancer cell line and the genes TXNL4B, FOXK1, PTPRJ, and SNN were candidates for the IPA220 gastric cancer cell line." (PMID 19563644, 2009).
lung squamous cell carcinoma (2 papers, 2021 to 2022). "The mRNA and protein expression of BMP5 in LUAD tissue were remarkably high compared with lung squamous cell carcinoma tissue." (PMID 34036102, 2021). "In 2015, researchers from Huazhong University of Science and Technology conducted transcriptomics level analyses on human lung squamous cell carcinoma, confirming the driver role of BMP3 and BMP5 at the transcriptomics levels." (PMID 35155435, 2022).
metastatic carcinoma (2 papers, 2020 to 2021). A carcinoma which has spread from the original site of growth to another anatomic site. "BMP5 and GDF10 (BMP3b) expression was particularly altered by changes in ERK1/2 activation, although the functions of these genes in breast and metastatic cancers have not been well characterized." (PMID 34588427, 2021).
myopia (2 papers, 2011 to 2025). "By comparing the myopic eyes and the control eyes of the guinea pigs, the expression of BMP-2 and BMP-5 decreased in the myopic eyes, suggesting that they were associated with scleral remodeling during the myopia induction." (PMID 40696418, 2025). "Based on these studies, BMP-2 and BMP-5 are assumed to be involved in the development of myopia and their expression is seen to decrease during this process." (PMID 40696418, 2025). "The decreased expression of BMP-5 indicates that BMP-5 was involved in sclera remodeling during myopia induction." (PMID 21403850, 2011).
Obesity (2 papers, 2018 to 2020). Accumulation of substantial excess body fat. "The significant genes in GWAS results (CALCR, PLAG1, INSIG2, PPARG, BMP5, S100A10) also have been identified to have relationship with growth performance and obesity of adipose tissue for pig and cattle." (PMID 33264312, 2020).
osteosarcoma (2 papers, 2009 to 2023). A usually aggressive malignant bone-forming mesenchymal neoplasm, predominantly affecting adolescents and young adults. "Interestingly, in both leiomyosarcoma and osteosarcoma, an upregulated gene was BMP5, which encodes a secret ligand of the TFG-beta (transforming growth factor-beta) protein family and is associated with bone and cartilage development." (PMID 36673024, 2023). "The various haplotypes of D6S1276 and SNPs rs9475431, rs9475430, and rs9475429 were then subcloned into the BMP5 Promoter-Luciferase construct and transiently transfected into MG63 (human osteosarcoma), CH8 (human articular chondrocytes), and SW872 (human liposarcoma) cells." (PMID 20021689, 2009).
rectum adenocarcinoma (2 papers, 2018 to 2020). An adenocarcinoma arising from the rectum. "The analysis showed that BMP5 was significantly co-expressed with ACVR1C in mixed lobular and ductal breast, invasive lobular breast, colon, rectal mucinous, cecum mucinous and rectum adenocarcinoma." (PMID 31973134, 2020).
squamous cell carcinoma (2 papers, 2020). A carcinoma arising from squamous epithelial cells. "The overexpressed BMP5 mRNA has also been found in the squamous cell carcinoma." (PMID 31973134, 2020).
adenoma (1 paper, 2018). A neoplasm arising from the epithelium. "We analyzed GEO datasets that recruit normal tissue and adenomas (polyps) and found BMP5 downregulation is an early event in CRC." (PMID 30572883, 2018). "Loss of BMP5 is predominant in CRC, indicating it may be an early event of normal epithelium-adenoma transition." (PMID 30572883, 2018).
benign prostatic hyperplasia (1 paper, 2006). A non-cancerous nodular enlargement of the prostate gland. "Little is know about BMP5 with regard to the prostate, although its expression has been observed to be increased in benign prostatic hyperplasia." (PMID 16638148, 2006).
bladder cancers (1 paper, 2020). "On the other hand, investigation on bladder cancer prognosis relevance using PROGgene V2 database recommends a positive relation between lower BMP5 expression and lower relapse-free survival." (PMID 31973134, 2020). "In GSE31684 dataset, relapse-free survival was significantly low in bladder cancer patients with the low expression level of BMP5 compared to their higher expression counterparts (Cox p-value: 0.0222747)." (PMID 31973134, 2020). "PROGgene V2 database was used to determine the prognosis of BMP5 expression with bladder cancer." (PMID 31973134, 2020).
brain ischemia (1 paper, 2022). Diminished or absent blood supply to the brain caused by obstruction (thrombosis or embolism) of an artery resulting in neurologic damage. "Our screen experiment showed that most BMP family members, including BMP2, BMP4, BMP5, and BMP7 increased transiently at 24 h after brain ischemia." (PMID 34904361, 2022).
cardiomyopathies (1 paper, 2019). "We identified 250 down-regulated genes, with many of them known to be important for heart development, such as Ttn, Cav1, Bmp5, and Actc1; Go Ontology (GO) analysis showed that these genes are important for maintaining normal heart function or are closely implicated in cardiomyopathies." (PMID 31541101, 2019).
CNS cancers (1 paper, 2020). "Our analysis revealed that BMP5 was down-regulated in breast, coloretal, lung, bladder and ovarian cancers, but was over-expressed only in brain and CNS cancers as compared to that in normal tissue." (PMID 31973134, 2020). "The BMP5 gene expression in breast, bladder, colorectal, lung and ovarian cancer cells was found lower in compared to normal cells, whereas, it was higher in the brain and CNS cancer." (PMID 31973134, 2020).
fractures (1 paper, 2022). "A similar methodology was also used to detect enhancers that direct Bmp5 expression in developing mice, providing a basis to identify regulatory regions that act specifically to drive reparative Bmp5 following bone fractures and soft tissue injuries to the lung and skin." (PMID 36252130, 2022).
granulosa cell tumor (1 paper, 2021). A slow-growing, malignant tumor, characterize by the presence of granulosa-like cells and Call-Exner bodies, that is almost always found in the ovary. "Although predicted deleterious variants in PIK3C2G, BMP5, and LRP2 were found, we could not identify an overlapping genetic variant or affected locus that may explain a genetic predisposition for granulosa cell tumors." (PMID 34069790, 2021).
iron overload (1 paper, 2025). "Both BMP5 and BMP6 are strong regulators of hepcidin expression, and the hepcidin levels cannot be increased in BMP5 and BMP6 double-deficient mice as response to iron overload." (PMID 39965404, 2025).
malaria (1 paper, 2024). Malaria is a serious and sometimes fatal disease caused by a parasite that commonly infects a certain type of mosquito which feeds on humans. "In the convalescent phase of malaria, BMP5 a ligand of the TGF-beta superfamily that can lead to the recruitment and activation of SMAD family transcription factors is downregulated." (PMID 37831367, 2024).
malignant schwannoma (1 paper, 2020). "In addition, the BMP-5 mRNA level in malignant schwannoma was relatively lower than that in benign lesions." (PMID 32050622, 2020).
myocardial infarction (1 paper, 2025). Gross necrosis of the myocardium, as a result of interruption of the blood supply to the area, as in coronary thrombosis. "For instance, BMP5 has been shown to promote the survival of various cell types, including cardiomyocytes after myocardial infarction, neural crest progenitor cells and sciatic nerve cells." (PMID 40471239, 2025).
nerve sheath tumors (1 paper, 2020). "In peripheral nerve and neoplastic lesions of nerve sheath tumors, BMP-5 contributed to the maintenance of health, control of proliferation, and neoplastic transformation of the peripheral nervous system." (PMID 32050622, 2020).